LYVE1 (lymphatic vessel endothelial hyaluronan receptor 1)
Diseases named in the same sentence as LYVE1 in open-access papers (continued):
Sharing a sentence is not in itself a finding about the gene and the disease.
tumor (continued). "Tumours with confirmed p16 induction (+Dox) contained less Lyve-1 positive lymphatic vessels than control tumours (33% reduction, P=0.0299)." (PMID 18577984, 2008). "Immunostaining with the antibody to the LYVE-1 HA receptor identified irregularly shaped, thin walled lymphatics in the capsular and intratumoural regions of the tumour with capsular lymphatics being more frequent than intratumoural lymphatics." (PMID 16685274, 2006). "The level of LYVE-1 mRNA expression in tumour samples was shown to be a sensitive indicator of the level of lymphangiogenesis in vivo." (PMID 16570043, 2006). "More recently, however, the development of specific markers such as the lymphatic hyaluronan receptor LYVE-1, the subject of this manuscript, has allowed many new experimental studies of tumour lymphatics to be initiated." (PMID 16251871, 2005). "Based on similar findings in tumours by Padera the specificity of LYVE-1 for lymphatics has recently been questioned." (PMID 16251871, 2005). "It is possible that there are more of these in tumours further explaining our findings of erythrocytes in LYVE-1 positive vessels." (PMID 16251871, 2005). "In the liver metastases of BC and CRC with a replacement growth pattern, the blood vessels close to the interface, but well surrounded by tumour cells, continued to express LYVE-1." (PMID 15054467, 2004). "However, we previously showed that myeloid-specific proteins CD14, CD68, and PU-1 are intracellularly expressed in LYVE-1+ tumor vessels, suggesting their full merging with myeloid cells." (PMID 40507286, 2025). "Consequently, we propose that Nans depletion, decreasing the sialylation level of tumor cells, play a contributory role in reversing the immunosuppressive microenvironment by impeding the infiltration of Lyve1+ macrophages." (PMID 40180929, 2025). "Recent evidence suggests that lymphatic vascular biomarkers such as the Vascular Endothelial Growth Factor (VEGF)-R3, LYVE-1, podoplanin, and Prox-1 (prospero-related homeobox-1) play crucial roles in promoting lymphangiogenesis and facilitating tumor dissemination to axillary lymph nodes." (PMID 40647432, 2025). "As lower expression of Lyve1 in tumor sites was identified by spatial transcriptomics analysis in this study and lymphatic angiogenesis was often driven by VEGF-families, we subsequently explored the correlation of VEGF-families with CCL21, CCL19, Pecam1 (CD31) and Lyve1 by the TCGA database of HCC." (PMID 40685403, 2025). "Therefore, it was evident that AA exerted its influence on tumor growth inhibition and metastasis prevention through the regulation of Hsp90, LYVE-1, and VEGF-C protein expression." (PMID 40066340, 2025). "Similarly, quercetagitrin enhanced the inhibitory effects of defactinib and ponatinib on the expression of CDK7/9, Ki67, and LYVE1 in primary tumor tissues and the activation and expression of Yamanaka transcription factors in lymph nodes." (PMID 40887473, 2025). "Additionally, targeting the IFN-γ receptor on LECs in a metastatic tumor model led to increased LYVE-1 expression and reduced tumor burdens." (PMID 40655011, 2025). "In contrast, MFPs from tumor-free mice contained only 20–28% marker-positive Lyve-1+ cells." (PMID 40507286, 2025). "LYVE-1+ macrophages in the BC tumor microenvironment may affect tumor progression and immune responses through multiple mechanisms, such as forming multicellular nesting structures, inducing immunosuppression, and influencing tumor angiogenesis and metastasis." (PMID 40881682, 2025). "In addition to tissue remodeling, LYVE‐1+ macrophages, also marked by TIM4 and FOLR2, are also associated with immune regulation in the tumor microenvironment." (PMID 38426622, 2024). "Additionally, the anti-lymphangiogenesis activity of anlotinib was further confirmed via immunofluorescence staining of 4T1 and CT26 tumor tissues, as evidenced by the decreased expression of LYVE-1." (PMID 38616190, 2024).
tumor (continued). "However, tracking tumor-recruited GFP-positive cells showed that Lyve-1+, Ter-119+ and CD3e+ subsets were segregated and localized to distinct intratumoral sites." (PMID 38640116, 2024). "Moreover, SiHa‐LNM2 cells significantly enhanced LYVE‐1 positive vessel formation in both the intratumoral and peritumoral areas of the primary footpad tumor." (PMID 39119899, 2024). "Furthermore, LYVE-1+ and F4/80+ macrophages were found to localize in close proximity to HA dense tumor regions within the peritumoral stroma." (PMID 38717149, 2024). "While the role of LYVE-1–expressing macrophages in regulating HA has not been previously investigated in the context of tumor-associated macrophages, we have shown that LYVE-1+ macrophages localize to HA-enriched regions in the normal mammary gland." (PMID 38717149, 2024). "Understanding phenotypic macrophage subsets, such as the tumor-supporting LYVE-1+ macrophages, may provide additional viable targets for improved cancer therapeutics." (PMID 38717149, 2024). "While PDPN was evenly expressed by all LECs as expected, normal LECs retained high LYVE-1 expression whereas tumor-associated LECs were largely LYVE-1 negative." (PMID 38361951, 2024). "In addition to tissue remodeling, the results from the scRNA-seq analysis demonstrate that LYVE-1+ macrophages promote an anti-inflammatory tumor microenvironment." (PMID 38717149, 2024). "Immunohistostaining of lymphatic vessel endothelial hyaluronan receptor 1 (Lyve-1) on tumor-draining lymph nodes (TDLNs) also indicated that the scramble group tumors promoted axillary lymph node metastasis with increased lymphangiogenesis when left unresected." (PMID 38505617, 2024). "The Y949F mutation did not affect tumor-induced lymphangiogenesis, as shown by the unperturbed LYVE-1+ lymphatic vessel density at the tumor periphery in the B16F10-engrafted Vegfr2Y949F/Y949F and WT mouse ears." (PMID 38148112, 2024). "Furthermore, immunofluorescence double staining was conducted on footpad tumor tissues to identify Ki67 and LYVE1." (PMID 39382373, 2024). "Furthermore, the results demonstrate that the LYVE-1+ macrophage population maintains an anti-inflammatory tumor microenvironment, supports tumor growth, and restricts CD8+ T-cell count." (PMID 38717149, 2024). "Lyve‐1+ mesothelial macrophages promote tumor growth in omentum." (PMID 39494816, 2024). "In the subcutaneous xenograft tumor model, the positive rates (percentage expression) of LYVE-1, VEGF-C and VEGFR-3 in the control group were 47.28 ± 1.17%, 41.84 ± 0.83%, and 50.18 ± 1.71%, respectively, and those in the PZH group were 28.37 ± 1.67%, 18.39 ± 1.11%, and 26.71 ± 0.62%, respectively." (PMID 37286729, 2023). "LYVE-1 is a specific marker of HLECs, which can reflect the density of tumor-related lymphatics." (PMID 37286729, 2023). "Pharmacological inhibition of LYVE1 suppresses the vasculature content and tumor angiogenesis." (PMID 37810197, 2023). "Furthermore, F4/80 + cells had robust expression of the HA receptor, Lyve1, in the aggressive tumor models." (PMID 36723776, 2023). "Since CXCR4 was highly expressed across most T cell subsets in BrM.ICB, the MRC1+LYVE1+ macrophage population could recruit these T cells into the BrM tumor parenchyma through CXCR4:CXCL12 interactions." (PMID 37655659, 2023). "In the orthotopic xenograft tumor model, the positive rates of LYVE-1, VEGF-C, and VEGFR-3 in the control group were 29.00 ± 1.42%, 45.41 ± 0.93%, and 51.80 ± 0.19%, respectively, and those in the PZH group were 19.25 ± 1.25%, 27.55 ± 1.52%, and 31.61 ± 1.15%, respectively." (PMID 37286729, 2023). "The tumor MLVD was further determined by LYVE‐1 positive signals." (PMID 37184125, 2023). "Moreover, tumor-recruited Lyve-1+ lymphatic progenitors in vivo expressed all Th2 receptors as well as corresponding ligands, including IL-4 and IL-13, which were absent in BM cells." (PMID 35442077, 2022).
tumor (continued). "However, in tumor-free Lyve-1-KO livers numbers of hepatic CD4+, CD8+ and regulatory T cells were increased." (PMID 36496412, 2022). "Regarding cancer metastasis, in vitro studies imply LYVE-1 to be involved in tumor cell adhesion." (PMID 36496412, 2022). "Ki67, CD31 and LYVE1 are specific markers for nuclear proliferation, vascular endothelial cells and lymphatic vessels, respectively, which are key for tumor metastasis and malignancy." (PMID 36297592, 2022). "By immunofluorescence staining of the tumor tissues, we could see co-expression areas of LYVE-1 positive and claudin-3 positive staining in claudin-3+/+ mice." (PMID 36261482, 2022). "Furthermore, PBMF markedly reduced lymphatic vessel density (LVD) (labeled by LYVE-1) in recurrence tumor tissues, and mRNA levels of VEGF-C/D, VEGFR-2/3 of recurrence tumors were all significantly lower in the high-dose group." (PMID 36056333, 2022). "LYVE-1/Lyve-1 is expressed on lymphatic endothelium, subsets of vascular endothelial cells, for example LSECs, and on subgroups of macrophages, such as certain tumor-infiltrating macrophages." (PMID 36496412, 2022). "Besides ECs, subtypes of macrophages, such as some tumor-infiltrating macrophages, also show expression of LYVE-1/Lyve-1." (PMID 36496412, 2022). "A single previous report identified acetylated α-tubulin+ structures on LYVE-1+ cells in thin sections of pancreatic ductal adenocarcinoma, suggesting that primary cilia may modulate tumor-stroma interactions in the tumor microenvironment." (PMID 34055805, 2021). "Interestingly, knockdown of LYVE-1 inhibited the capacity of tumor cells to generate consistent LM-vessels in vitro, and reduced tumor cell metastasis in vivo." (PMID 35048009, 2021). "LYVE1 acts as a receptor and binds to both soluble and immobilized hyaluronan, may function in lymphatic hyaluronan transport and tumor metastasis." (PMID 33717664, 2021). "LYVE-1 (lymphatic vessel hyaluronan receptor-1), one of the most widely used and specific markers for lymphatic endothelial cells, was fluorescently labeled to measure the primary tumor lymphatic vessel density." (PMID 34299365, 2021). "Importantly, the siRNA-mediated knockdown of LYVE-1 not only impaired tumour cell migration but also blunted their capacity to form LM-vessels in vitro and reduced tumour metastasis in vivo." (PMID 33674563, 2021). "Moreover, intratumor STING activation promoted tumor vascular normalization, increased the density of Lyve-1+lymphatic endothelial cells, enhanced tumor infiltration of CD8+T cells and CD11c+ DCs, promoted the local TLS neogenesis, and slowed melanoma growth." (PMID 34553849, 2021). "CD32b, together with stabilin-1, stabilin-2, and lymphatic vessel endothelial hyaluronan receptor-1 (LYVE-1), were sequentially lost during tumor progression in mice with inducible HCC (AST model), as well as in human HCC patients (examined in tissue microarrays)." (PMID 34707514, 2021). "LYVE-1 is further suggested to have a role in wound healing and tumor formation." (PMID 34707514, 2021). "Additionally, we examined tumor metastasis using cytokeratin (epithelial cells marker) and LYVE-1 (lymphatic vessels marker) in cytokeratin+ tumor cells and found that TFG and TFMG significantly reduced metastasis to inguinal lymph nodes." (PMID 32928251, 2020). "LYVE-1 is a predictor of lymphatic vessel formation in tumours." (PMID 31892990, 2020). "Meanwhile, LYVE1 marked lymphadenogenesis, which promoted tumor cell dissemination." (PMID 32852285, 2020). "Lymphatic vessels in tumor tissues were marked with LYVE-1 by immunofluorescence." (PMID 33643892, 2020). "The immunohistochemical factors of lymphatic endothelial cells, such as D2-40 (podoplanin), lymphatic vessel endothelial hyaluronic acid receptor 1 (LYVE1), and VEGF receptor-3 (VEGFR-3), indicate the lymphatic vessel count associated with the tumor which can metastasize to lymph nodes." (PMID 31870093, 2019).
tumor (continued). "Importantly, phomaketide A impeded tumor growth and lymphangiogenesis by decreasing the expression of LYVE-1, a specific marker for lymphatic vessels, in tumor xenograft animal model." (PMID 30959907, 2019). "We have also previously shown expression of CD31, VEGFC, and LYVE1 to be high in this tumour set." (PMID 31277414, 2019). "With the discovery of molecules targeted at the lymphatic system such as lymphatic vessel endothelial hyaluronan receptor 1 (LYVE-1) and Podoplanin, many studies have been performed to determine the role of lymphatic endothelial cells (LECs) in tumor metastasis." (PMID 31289961, 2019). "mECK36 tumor formation show consistent expression of the KS markers Podoplanin and LYVE-1, occurring with concomitant up-regulation of KSHV lytic oncogenes and angiogenesis ligands/ receptors, pointing to the upregulation of various receptor tyrosine kinase signaling axes." (PMID 29985958, 2018). "LYVE-1-positive lymphatic vessels invaded by tumor clusters were occasionally observed." (PMID 29977159, 2018). "By contrast, few LYVE-1-positive vessel-like structures were observed in PTBP3-knockdown tumours." (PMID 29752441, 2018). "Thus, the functional role of LYVE-1 in lymphatic vessels, inflammation, and tumor lymphangiogenesis are vital areas of pre-clinical investigation." (PMID 28439123, 2017). "To evaluate, whether LYVE-1+ TAMs are involved in angiogenic processes in hypoxic regions of the tumor, wild type B16F1 tumors were stained and analyzed." (PMID 29262593, 2017). "Both of the positive expression rates of LYVE–1 in tumor tissues and para-cancerous tissues were 100%, and the same results could be found for Podoplanin." (PMID 29162097, 2017). "Extensive shedding of LYVE-1 in the tumor microenvironment is, therefore, conceivable." (PMID 29262593, 2017). "The expression level of LYVE–1 in tumor tissues of patients with lymph node involvement was similar with that in patients without lymph node involvement (P = 0.354), and the similar results were found for VEGFR–3 (P = 0.631), Podoplanin (P = 0.490), and Prox–1 (P = 0.503)." (PMID 29162097, 2017). "LYVE-1-positive vessels with intraluminal ferritin were seen frequently in both the periphery and central regions of BK-12 and LA-19 tumors, suggesting the presence of functional intratumoral lymphatics in both tumor models." (PMID 27486768, 2016). "In addition, licoricidin reduced the expression of VEGF-C, VEGF-R3, and LYVE-1, a specific lymphatic endothelium marker, in tumor tissues." (PMID 27314329, 2016). "Tumor lymphangiogenesis was analyzed using immunohistochemical staining with LYVE-1 antibody." (PMID 27190997, 2016). "Additionally, a decrease in protein expression of VEGF-R2, VEGF-C, VEGF-R3, and LYVE-1 was noted in tumor tissues of licoricidin-treated mice." (PMID 27314329, 2016). "Additionally, HFD feeding significantly increased the expression of proteins related to angiogenesis (VEGF-A, VEGFR-2, and CD31) and lymphangiogenesis (VEGF-C, VEGF-D, and LYVE-1) in tumor tissues." (PMID 25912035, 2015). "In contrast to PROX1, expression of LYVE1, one of the most widely used markers of LECs in normal and tumor tissues, was restricted to the paracortical and medullary sinuses in most LNs, and was not expressed by PROX1+ LECs in the subcapsular and trabecular sinuses." (PMID 24733110, 2014). "The recent introduction of LYVE-1 and D2-40 has paved the way for exciting research into the field of lymphangiogenesis: its mechanisms and the possible role these vessels play in the spread and dissemination of tumor cells." (PMID 24963215, 2014). "Tumoral lymphatics were delineated with both Evan’s blue and LYVE-1 immunostaining." (PMID 24502459, 2014). "Nevertheless, HA on the surface of tumor cells may influence tumor adhesion through interactions with the LYVE-1 found on lymphatic endothelial cells." (PMID 23717428, 2013).
tumor (continued). "To directly investigate whether the LYVE-1-HA interaction influences tumor lymph metastasis, we examined the adhesive ability of tumor cells (different HA content) to LYVE-1-positive cells." (PMID 23717428, 2013). "Our study found that HA cables exist on some tumor cell surfaces and that HA is crossed as cables on the cell surface of tumors may activate LYVE-1." (PMID 23717428, 2013). "Indeed, hATM expressed both pro- and anti-inflammatory markers and the lymphatic vessel endothelial hyaluronan receptor 1 (LYVE-1), a specific marker of macrophages involved in tumor growth and wound healing, as well as in mouse AT angiogenesis." (PMID 22355352, 2012). "A review of the pathology of the primary tumour in these two cases showed that both tumours contained intratumoural lymphatics, as assessed by endothelial cell expression of the lymphatic markers, podoplanin and LYVE-1." (PMID 22612847, 2011). "During this process, LYVE-1 molecules may provide adhesive force for tumor cells and further promote tumor lymphatic invasion and lymph node metastasis." (PMID 19232130, 2009). "It has also been shown that LYVE-1 is involved in adherence of tumor cells." (PMID 19232130, 2009). "Confocal imaging revealed that 3% of Podoplanin+ tumor lymphatic endothelial cells (TLEC) as well as 3.5% of Prox-1+ or LYVE-1+ TLEC co-expressed GFP, indicating that approximately 3% of tumor-surrounding lymphatic endothelial cells are derived from the bone marrow." (PMID 19759906, 2009). "However, few LYVE-1 positive vessels were large blood vessels with smooth muscle, and tumor embolus were observed in their muscular layer and lumen." (PMID 19216806, 2009). "The lymphatics in a section of normal ovary and tumour stained LYVE-1 antibody." (PMID 16685274, 2006). "Besides lymphatic and sinusoidal vessel endothelium, LYVE-1 is also expressed in some macrophage-like cells present in inflamed tissue and in tumour infiltrates." (PMID 17117184, 2006). "Histopathological analysis revealed significantly increased α-SMA+ CAFs infiltration and Lyve-1+ lymphatic vessel density in primary tumors (pT) from H358-CAFs co-injected xenografts compared to H358-only controls, confirming the establishment of robust CAFs-rich, lymphangiogenic tumor models." (PMID 40575163, 2025). "Due to disbalance between the production and the release rates of BM cells in vivo, the Lyve-1+/Pdpn+ fraction of lymphatic progenitors accounted only for 6% of total cells, which is significantly lower than in an in vitro assay shielded from tumor-induced mobilization." (PMID 38640116, 2024). "However, multipotent CD11b+/Lyve-1+/Ter-119+/CD3e+ progenitors detected in BM appeared to split into a predominant myeloid-lymphatic fraction and minor subsets expressing erythroid and T-cell markers upon establishing tumor residence." (PMID 38640116, 2024). "Hence, LYVE-1 blockade might be most effective for the treatment of early-stage cancers, when administered after primary tumour resection, prior to nodal dissemination and local immune activation." (PMID 37606814, 2024). "In addition, increased apoptosis at the tumor margin in the depletion model could suggest that LYVE-1+ macrophages produce factors that promote survival specifically at the tumor margin." (PMID 38717149, 2024). "Furthermore, LYVE1-immunopositive cells were mostly found in the outer section of the tumor." (PMID 37237550, 2023). "Besides, adhesion of hyaluronan-expressing tumor cells to endothelial cells is mediated by Lyve-1." (PMID 36496412, 2022). "Stromal determinants were better predictors of response than tumor epithelial cells, and we identified alveolar epithelial and fibroblastic reticular cells as well as lymphatic vessel endothelial hyaluronan receptor 1–positive (Lyve1+) macrophages as putative drivers of therapeutic resistance." (PMID 33886505, 2021). "Moreover, strong positive staining for LYVE‐1 was observed in some tumor cells." (PMID 31960509, 2020).